CFAP418 (cilia and flagella associated protein 418)
Description:
May be involved in photoreceptor outer segment disk morphogenesis (By similarity).
Synonyms: C8orf37; smalltalk; MOT25; FLJ30600; CORD16; RP64; BBS21; FAP418
Tractability: Antibody: the Human Protein Atlas places it where antibodies can reach.
Gene: Protein-coding gene on chromosome 8 (95,244,913 to 95,269,201, reverse strand). Ensembl gene ENSG00000156172.
Subcellular location: Cytoplasm; Photoreceptor inner segment
Subcellular location (Human Protein Atlas): Plasma membrane; Primary cilium; Cell Junctions; Centrosome; Vesicles
Gene Ontology:
Molecular function: protein binding
Biological process: photoreceptor cell morphogenesis
Cellular component: ciliary base; cytoplasm; photoreceptor inner segment
Genetic constraint (gnomAD): Loss-of-function variants: 13 observed, 12.4 expected, observed/expected ratio (o/e) 1.05, 90% interval 0.68 to 1.64. The upper end of that interval is the gene's LOEUF score, 1.64, which puts it in group 6 of 6, group 1 being the genes least tolerant of losing a copy. Missense variants: 172 observed, 177.04 expected, observed/expected ratio (o/e) 0.97, 90% interval 0.86 to 1.1. Synonymous variants: 48 observed, 63.12 expected, observed/expected ratio (o/e) 0.76, 90% interval 0.6 to 0.97.
Gene-disease validity (ClinGen):
ClinGen rates the evidence that CFAP418 causes each of these diseases.
ciliopathy (autosomal recessive): Definitive. A genetic disorder of the cellular cilia or the cilia anchoring structures, the basal bodies, or of ciliary function.
Homologues: Orthologues: chimpanzee CFAP418 (99% identical), macaque CFAP418 (96% identical), rabbit CFAP418 (84% identical), pig CFAP418 (81% identical), rat Cfap418 (80% identical), mouse Cfap418 (78% identical), dog CFAP418 (77% identical), guinea pig CFAP418 (77% identical), tropical clawed frog cfap418 (48% identical).
Diseases named in the same sentence as CFAP418 in open-access papers:
CFAP418 is named in the same sentence as 13 diseases in open-access papers, as found by Europe PMC text mining. Sharing a sentence is not in itself a finding about the gene and the disease. The quoted sentences say what the papers report.
Bardet-Biedl syndrome (4 papers, 2017 to 2024). A ciliopathy with multisystem involvement. "Cilia- and flagella-associated protein 418 (CFAP418) is a causative gene for retinitis pigmentosa, cone-rod dystrophy, Bardet-Biedl syndrome (BBS), and combined retinal dystrophy and macular atrophy." (PMID 37971880, 2024).
cone-rod dystrophy (3 papers, 2023 to 2025). Inherited retinal dystrophies that belong to the group of pigmentary retinopathies. "Biallelic pathogenic mutations in CFAP418 cause Bardet-Biedl syndrome and isolated retinopathies including cone-rod dystrophy (CRD) and retinitis pigmentosa (RP)." (PMID 41153400, 2025).
retinal degeneration (2 papers, 2021 to 2024). Degeneration of the retina. "Membrane lipid imbalance and abnormal membrane-associated cellular processes underlie CFAP418-associated retinal degeneration." (PMID 37971880, 2024).
CFAP418 also shares sentences with these, for which no sentence is quoted: retinitis pigmentosa (3 papers); myopia (2); cancer (1); ciliopathies (1); generalized dystonia (1); genetic disorders (1); macular degeneration (1); prostate carcinoma (1); Retinal dystrophy (1); tumor (1).